CAPG (capping actin protein, gelsolin like)
Diseases named in the same sentence as CAPG in open-access papers (continued):
Sharing a sentence is not in itself a finding about the gene and the disease.
cancer (49 papers, 2008 to 2025). A tumor composed of atypical neoplastic, often pleomorphic cells that invade other tissues. "Such downregulation is particularly relevant, as CapG overexpression has been linked to poor prognosis and increased invasiveness in colorectal and other cancers." (PMID 41515404, 2025). "The CAPG gene, known for its aberrant expression in various cancers and its association with tumour invasion and metastasis, has emerged as a potential player in HCC." (PMID 40982354, 2025). "On the other hand, DKK1, CTSB, CTSD, BCLX, CSF1, and CAPG are associated with the metastatic potential of cancer." (PMID 35745691, 2022). "A meta-analysis revealed that CapG was associated with poor prognosis in a variety of malignant tumors." (PMID 36258216, 2022). "Another gelsolin family member, macrophage-capping protein (CapG), is proposed to be a diagnostic biomarker, indicator of prognosis, and predictor of response to treatment across numerous cancer types." (PMID 34948433, 2021). "Most of the literatures have demonstrated that CapG is associated with invasion and migration of cancer cells." (PMID 30155403, 2018). "CAPG encodes an actin filament end capping of the gelsolin family crucial for the control of cell migration or invasion in a variety of cancer cells." (PMID 21081927, 2011). "DKK1, CTSB, CTSD, and CAPG are also associated with the metastatic potential of cancer." (PMID 37439806, 2024). "With OC being one of the most lethal cancer diseases, the detection of novel biomarkers such as CapG could reveal new diagnostic and therapeutic targets." (PMID 24804218, 2014). "The suppression of the expression of GA-upregulated cancer proteins, including enolase-2, capping protein CapG, galectin-3, and cathepsin D, was observed after p70S6K1 downregulation/blockade." (PMID 40149589, 2025). "Cumulatively, these findings underscore CAPG as a multifaceted regulator in cancer, influencing metastasis, ferroptosis, and signalling pathways across diverse malignancies." (PMID 40982354, 2025). "The capping actin protein, gelsolin-like (CAPG), also known as Macrophage Capping Protein, regulates cell motility by remodeling actin filaments, which participate in cell migration and invasion in several types of cancers." (PMID 39600941, 2024). "Upregulation of CAPG has been observed in a variety of cancer tissues, including prostate, ovarian, pancreatic, and breast tissues, and our study confirmed that CAPG expression was upregulated in GC." (PMID 38191512, 2024). "Studies on the status of natural killer (NK) cells in TME and NK heterogeneity have shown that NK cell population preferentially expressing CAPG is closely related to tumor metastasis, which is crucial for the understanding of cancer immunotherapy." (PMID 39600941, 2024). "As a prerequisite for tumor cell invasion and metastasis, CAPG can mediate cell migration in both normal and cancer cells." (PMID 38191512, 2024). "Repeated FRAP of CapG in the cancer cell nucleus permits assessment of the functionality of signaling cascades on the single cell level provided those signaling cascades affect CapG shuttling." (PMID 39369027, 2024). "CAPG has been reported as a potential prognostic biomarker and potential clinicopathological predictor of various cancers." (PMID 39600941, 2024). "CCK8, colony formation, and EdU incorporation assays indicated that the knockdown of CAPG markedly reduced cancer cell proliferation compared to that observed in the negative control." (PMID 37198416, 2023). "CapG-GFP shuttles faster into the cancer cell nucleus of the MDA-MB-213 cell than into the cell nucleus of MCF-12A." (PMID 36230711, 2022). "In conclusion, our small-molecule-based screening has identified two human cancer-related genes (Nectin-4 and CapG), whose translation is suppressed by the RNA G-quadruplexes." (PMID 35801908, 2022).
cancer (continued). "The approach described in the present study allowed us to identify two human-cancer-related genes (Nectin-4 and CapG), whose translation is suppressed by the RNA G-quadruplexes." (PMID 35801908, 2022). "By n contrast, CapG was previously reported to contribute to tumour invasionand metastasis in multiple human cancers." (PMID 32187327, 2020). "In recent years, several proteomic studies demonstrated that CAPG is overexpressed in various types of cancer, which enhances cellular motility/chemotaxis, and are associated with increased invasion into collagen type I or chick heart fragments." (PMID 27351483, 2016). "We showed that CapG nanobodies can be delivered into cancer cells by using bacteria harboring a type III protein secretion system (T3SS)." (PMID 24330716, 2013). "Experimental evidence has shown that CapG also is crucial for regulating cell motility; however, its exact function in the development and progression of malignant tumours remains controversial." (PMID 18237446, 2008). "CapG has generated great interest due to its oncogenic function in the control of cell migration or invasion in a variety of cancer cells." (PMID 18237446, 2008). "Conversely, CAPG, AVIL, and SVIL expression negatively correlated with anticancer immune cells and positively correlated with immunosuppressive cells like TAMs, Tregs, Th2 cells, MDSCs, and cancer‐associated fibroblasts (CAFs)." (PMID 39964147, 2025). "Additionally, we compared the differences in CAPG expression between normal and cancer cell lines and found that both mRNA and protein levels of CAPG in cancer cell lines were higher than in CD34+ HSPC." (PMID 38700746, 2025). "Additionally, CAPG can regulate the resistance and sensitivity of cancer cells to chemotherapeutic drugs." (PMID 38700746, 2025). "CapG was found to be overexpressed in cancer including breast and ovarian cancer." (PMID 39369027, 2024). "Several aspects of the intracellular mobility and compartmentalization of CapG in the living cancer cell which we had characterized previously made us consider using repeated FRAP of the nuclear fraction of CapG as a functional single cell readout for intracellular signaling." (PMID 39369027, 2024). "To first assess if our repeat FRAP assay could resolve differences in the CapG nuclear transport in the same live cancer cell, we tested its energy dependence which had been reported in in vitro experiments." (PMID 39369027, 2024). "Especially the nuclear fraction of CapG has been hypothesized to be critical for cancer cell invasion." (PMID 39369027, 2024). "Repeated FRAP of CapG in the cell nucleus is a suitable functional assay to assess downstream effects of signaling cascades in the single living cancer cell and demonstrated that CapG’s nuclear shuttling increased within minutes after EGF stimulation and depends on the phosphorylation of serine S70." (PMID 39369027, 2024). "Capping actin protein, gelsolin-like (CAPG) is a potential therapeutic target in various cancers." (PMID 39600941, 2024). "While the function of CapG in the cell nucleus remains unknown, it has been hypothesized that the nuclear CapG fraction is relevant for cell migration and cancer cell invasiveness." (PMID 39369027, 2024). "Studies have reported that CAPG, as a tumor-promoting gene, may mediate the occurrence and development of various cancers." (PMID 37198416, 2023). "Finally, elevated CAPG expression is correlated with unfavorable clinical parameters and poor patients` outcomes in different cancers, suggesting a potential role as a biomarker for prognosis and prediction of therapy outcome." (PMID 36993823, 2023). "In this report, our ChIP-qPCR data, and that the CAPG gene potentially contains a homology sequence with basis helix-loop-helix family DNA-binding proteins (bHLH) constitute strong pieces of evidence to suggest that CapG plays a role as a transcription factor in immune cells and cancer cells." (PMID 37454739, 2023).
cancer (continued). "In comparison with beta-catenin, few is known about the role of CapG in cancer." (PMID 36230711, 2022). "CapG has been reported of oncogenic functions in a variety of cancers." (PMID 36258216, 2022). "CAPG, which could be detected in the cytoplasm of normal liver tissue and HCC specimens, might contribute to tumor motility and cancer-associated mortality and be regarded as a prognostic or diagnostic biomarker for metastatic HCC." (PMID 34109210, 2021). "Similar to the cytokine profiling results, most of the cancer‐associated proteins, such as ANGPTL4, KLK5, GAL3, VIM, HERs, CAPG, HO, CTSD, and AFP were produced at higher levels on the aged matrix, but were reduced to young matrix levels after LOX siRNA treatment." (PMID 34617419, 2021). "Moreover, increased CapG expression has been found in several metastatic cancers, suggesting its role in cancer cell invasion and metastasis 7-9." (PMID 31660072, 2019). "CapG has been showed to overexpress and contribute on malignancy in multiple human cancers." (PMID 30155403, 2018). "In addition, capping actin protein (CapG) belongs to the gelsolin family and has been reported to contribute on tumor invasion/metastasis in multiple human cancers." (PMID 30155403, 2018). "Conversely, downregulation of CapG expression reduces invasion of various cancer cell lines." (PMID 24330716, 2013). "PPM1A, SNRPN, RAB5B, and CAPG were also reported to be related to cancer." (PMID 18237428, 2008). "Furthermore, the CAPG gene is strongly correlated with the development and emergence of cancers." (PMID 38700746, 2025). "Similarly, CapG and ACTA1, which are major components of the cell cytoskeleton, are also implicated in cancer initiation and progression and are linked to the outcome of cancer patients." (PMID 37958747, 2023). "Our work directly addresses this void by defining CAPG‐driven ferroptosis regulation as a novel therapeutic target, thereby advancing HCC treatment strategies beyond prior pan‐cancer studies." (PMID 40982354, 2025). "Here, we revealed the functions of CAPG, together with CLTA, in regulating the internalization of sEVs by cancer cells." (PMID 37354358, 2023). "In our study, CAPG was significantly upregulated in HCC cells, and the knockdown of CAPG markedly reduced cancer cell proliferation, suggesting that CAPG is critical for HCC cell proliferation." (PMID 37198416, 2023). "Some studies have explored the roles of SLC7A11, CAPG, and SQSTM1 in cancer." (PMID 37198416, 2023). "Analysis of the protein and mRNA products of 84 cancer-related human genes identified Nectin-4 and CapG as G-quadruplex-controlled genes whose mRNAs harbor non-canonical G-quadruplex structures on their 5′UTR region." (PMID 35801908, 2022). "Moreover, macrophage-capping protein (CAPG) has been shown to promote cancer metastasis, STC-1 enhances the invasion of cancer cells by activating PI3K pathway." (PMID 34513846, 2021). "However, earlier studies have reported CLU as down-regulated and CAPG and PRAME as up-regulated in advanced carcinomas compared to early tumours or normal tissue." (PMID 19775429, 2009). "Additionally, the association among circGLIS3, miR-449c-5p, CAPG, and GLIS3 was validated in both NHAs and GBM cells, indicating that it was not a cancer-specific relationship." (PMID 36114444, 2022). "Because conceptus and cancer cells possess various characteristics in common such as EMT and angiogenesis, it is considered that CAPG and AKR1B1 included in conceptus-derived exosomes could be involved in the conceptus attachment similar to those demonstrated in cancer adhesion and/or invasion." (PMID 27351483, 2016). "However, CAPG did not correlate with age, sex, or cancer differentiation." (PMID 38191512, 2024). "The results showed that apart from EPAS1 and RAD51AP1 that without immunohistochemistry data, SQLE, CAPG, RRM2, SLC1A5, and SRC as dangerous genes were higher expressed in cancer tissues." (PMID 37461802, 2023).
tumor (48 papers, 2008 to 2026). "Enrichment analysis indicated that CAPG is involved in immune-related pathways and is closely associated with the tumor microenvironment." (PMID 39600941, 2024). "The CapG protein expression levels in primary OSCCs were significantly associated with tumor size (P = 0.014)." (PMID 18237446, 2008). "CapG, crucial for actin filament dynamics and implicated in enhanced tumor cell motility, was suppressed by 17.6% in the KAE group and by 51.0% with cisplatin, highlighting a notable disruption of the cytoskeletal machinery required for movement and potential metastatic migration." (PMID 41515404, 2025). "Moreover, recent microarray analyses have shown associations between CapG expression and tumor prognosis with CapG overexpression in deceased patients with stage III serous OC in comparison to normal CapG expression in tumors of a survivor cohort." (PMID 24804218, 2014). "Enhanced expression of CapG was associated with large tumour size and advanced staging of OSCCs." (PMID 18237446, 2008). "We found CAPG significantly overexpressed in PDAC tissues (n = 179 tumor vs. 171 normal, p < 0.05), with levels correlating with advanced tumor stage (T3 vs. T1) and predicting poorer overall (p = 0.0085) and disease-free (p = 0.015) survival." (PMID 41915646, 2026). "Among the eight gelsolin superfamily genes, CAPG, VILL, and SVIL showed high associations with immune cell infiltration, highlighting their crucial roles in the tumor microenvironment (TME) and immunological function." (PMID 39964147, 2025). "Some studies have found that CAPG is overexpressed in some tumors and is related to the invasion, metastasis, and prognosis of the tumor." (PMID 38700746, 2025). "In summary, we elucidated a specific molecular mechanism through which CAPG promotes tumor proliferation and sorafenib resistance in HCC." (PMID 40959275, 2025). "The animal experiment results showed that in nude mice subcutaneously inoculated with SNU‐475 cells overexpressing CAPG and oe‐Ctrl, tumour volume was measured every 3–4 days." (PMID 40982354, 2025). "In this study, we demonstrated that CAPG promotes tumor proliferation and resistance to sorafenib in HCC by suppressing ferroptosis." (PMID 40959275, 2025). "CAPG, as an actin-binding protein, has been predominantly studied for its roles in tumor metastasis and migration of immune cells." (PMID 41050938, 2025). "In vivo, CAPG knockdown in combination with Dox treatment significantly inhibited tumour growth in nude mouse models (***p < 0.01)." (PMID 40982354, 2025). "We found that CAPG depletion inhibited tumor proliferation and metastasis both in vivo and in vitro." (PMID 40959275, 2025). "The results indicated that interference with CAPG significantly inhibited tumour growth in vivo when combined with Dox (10 mg/kg)." (PMID 40982354, 2025). "Suppression of CAPG expression inhibited tumor growth, metastasis, and sorafenib resistance both in vitro and in vivo." (PMID 40959275, 2025). "Subsequent in vitro and in vivo experiments demonstrated that CAPG knockdown inhibited tumor growth and metastasis." (PMID 40959275, 2025). "The results showed that CAPG expression was significantly increased in HCC tumours than that in normal controls (***p < 0.001)." (PMID 40982354, 2025). "SEPTIN-9 and CAPG consistently exhibited increased expression in both pathologies, indicating a shared structural organization in the cytoskeleton during tumour dormancy." (PMID 39223638, 2024). "These insights collectively emphasized the intrinsic relationship between CAPG expression and the complex tumor microenvironment." (PMID 39600941, 2024). "Ferroptosis analysis indicated that ALOX5 and VLDLR were the top CAPG-related ferroptosis markers; glutathione metabolism levels in tumor group were generally high, and decitabine was a ferroptosis inducer." (PMID 39600941, 2024).
tumor (continued). "The overexpression of CAPG in the cytoplasm of human HCC is associated with cell invasion, migration, and tumor prognosis in HCC." (PMID 37198416, 2023). "There are reports of overexpression of CapG in pancreatic cancer with a reportedly immunohistochemistry nuclear stain that correlated with increasing tumor size." (PMID 36230711, 2022). "Our investigations identified three major invasiveness biomarkers common to the three tumor sources, CAPG, FABP4, and LAMB2, and an additional set of 25 candidate biomarkers shared by rat and patient tumors." (PMID 32867073, 2020). "Herein, we confirm that CAPG is also increased in human MM cell lines, human MM tumor models, and patient MM." (PMID 32867073, 2020). "Further study demonstrates that knockdown of the expression of CapG in human CRC cells decreases the tumor migration ability." (PMID 30155403, 2018). "Although gelsolin has been reported to overexpress and induce tumor invasion in CRC cases, the role and the association of CapG with CRC are still unclear." (PMID 30155403, 2018). "Mean CapG expression level was calculated in normal tissue samples and CapG expression in each tumor sample was compared to mean expression in controls, consecutively." (PMID 24804218, 2014). "Capping protein (actin filament) gelsolin-like (CAPG), which was more expressed in tumours from deceased patients in our studies, belongs to the gelsolin protein superfamily." (PMID 19775429, 2009). "The CapG mRNA expression levels significantly increased in primary tumours of randomly selected CapG-positive cases (n = 10) compared with randomly selected CapG-negative cases (n = 10, Mann-Whitney U-test, P < 0.001)." (PMID 18237446, 2008). "Matched normal and tumour tissue sections of 79 human primary OSCCs and 28 OPLs were analyzed for CapG expression by immunohistochemistry (IHC)." (PMID 18237446, 2008). "Stromal components such as fibroblasts, lymphocytes, endothelial cells, and macrophages also exhibited positive CapG immunoreactivity, the last of which CapG is known to be homogeneously expressed in both normal and tumour specimens." (PMID 18237446, 2008). "In contrast, 41 of 79 (52%) cases of OSCCs examined had significantly increased expression of CapG immunoreactivity in the nucleus and cytoplasm of the tumour cells (IHC score > 78.68; maximum score of normal tissues)." (PMID 18237446, 2008). "Our findings demonstrate that CAPG drives tumor proliferation and sorafenib resistance by inhibiting ferroptosis, suggesting that CAPG may serve as a promising target in HCC." (PMID 40959275, 2025). "CAPG knockdown significantly reduced the tumor weight, volume, and growth rate." (PMID 40959275, 2025). "These study results indicate that the CAPG gene may promote tumor growth and have an important function in AML." (PMID 38700746, 2025). "The migration of tumor cells is an important step in tumor metastasis, and CAPG may affect the migration ability of tumor cells by regulating the dynamic changes of the cytoskeleton." (PMID 38700746, 2025). "CAPG knockdown significantly suppressed tumor weight and volume." (PMID 40959275, 2025). "Consequently, clinicopathological characteristics and the expression levels of GSN, SCIN, CAPG, VILL, VIL1, SVIL, and FLII were found to be closely associated with tumor stages in EC." (PMID 39964147, 2025). "The CAPG promoter methylation level in the primary tumor group was lower than in the normal group." (PMID 39600941, 2024). "The expression level of CAPG was relatively high in macrophages (Mar1, Mar2, Mar3, and Mar4) and other cell subsets, and CAPG was generally highly expressed in the tumor group." (PMID 39600941, 2024). "In addition, an investigation by TCGA database revealed that CAPG was statistically significantly highly expressed in a variety of tumor tissues compared to normal tissues." (PMID 37296281, 2023). "This implies that CAPG is closely related with tumor development." (PMID 37296281, 2023).